KLHL1 (kelch like family member 1)
Description:
May play a role in organizing the actin cytoskeleton of the brain cells.
Synonyms: KIAA1490; MRP2; FLJ30047
Tractability: Small molecule: it belongs to a druggable protein family. PROTAC: ubiquitination databases record sites on it.
Gene: Protein-coding gene on chromosome 13 (69,700,594 to 70,108,493, reverse strand). Ensembl gene ENSG00000150361.
Subcellular location: Cytoplasm, cytoskeleton
Gene Ontology:
Molecular function: protein binding; actin binding; ubiquitin-like ligase-substrate adaptor activity
Biological process: actin cytoskeleton organization; dendrite development; proteasome-mediated ubiquitin-dependent protein catabolic process
Cellular component: cytoplasm; Cul3-RING ubiquitin ligase complex; dendrite; neuronal cell body; cytoskeleton
Genetic constraint (gnomAD): Loss-of-function variants: 38 observed, 66.36 expected, observed/expected ratio (o/e) 0.57, 90% interval 0.44 to 0.75. The upper end of that interval is the gene's LOEUF score, 0.75, which puts it in group 3 of 6, group 1 being the genes least tolerant of losing a copy. Missense variants: 862 observed, 864.68 expected, observed/expected ratio (o/e) 1, 90% interval 0.94 to 1.05. Synonymous variants: 331 observed, 310.97 expected, observed/expected ratio (o/e) 1.06, 90% interval 0.97 to 1.17.
Homologues: Orthologues: chimpanzee KLHL1 (99% identical), macaque KLHL1 (99% identical), dog KLHL1 (97% identical), pig KLHL1 (97% identical), rabbit KLHL1 (97% identical), mouse Klhl1 (95% identical), rat Klhl1 (95% identical), guinea pig KLHL1 (79% identical). Paralogues in human: KLHL4 (64% identical), KLHL5 (63% identical), KLHL20 (34% identical), KLHL17 (33% identical), KLHL2 (31% identical), KLHL3 (31% identical), KLHL8 (30% identical), KEAP1 (28% identical), KLHL28 (28% identical), KLHL12 (28% identical), KLHL18 (28% identical), KLHL10 (25% identical), and 42 more.
Diseases named in the same sentence as KLHL1 in open-access papers:
KLHL1 is named in the same sentence as 14 diseases in open-access papers, as found by Europe PMC text mining. Sharing a sentence is not in itself a finding about the gene and the disease. The quoted sentences say what the papers report.
spinocerebellar ataxia type 8 (2 papers, 2014). Spinocerebellar ataxia type 8 (SCA8) is a subtype of type I autosomal dominant cerebellar ataxia (ADCA type I) characterized by cerebellar ataxia and cognitive dysfunction in almost three quarters of patients and pyramidal and sensory signs in approximately a third of patients. "Spinocerebellar ataxia type 8 (SCA8) is a dominantly inherited disorder caused by large CTG repeat expansions in the untranslated antisense RNA of the KLHL1 gene." (PMID 24959344, 2014).
Ataxia (1 paper, 2013). Ataxia refers to impaired coordination of voluntary muscle movement. "Secondly, partial loss of Klhl1 function with targeted deletion of a single Sca8 ataxia locus allele (including to overlapped KLHL1 gene) in mice leads to degeneration of Purkinje cell function, indicating an anti-sense RNA interference mechanism." (PMID 24040107, 2013).
autism (1 paper, 2020). Persistent deficits in social interaction and communication and interaction as well as a markedly restricted repertoire of activity and interest as well as repetitive patterns of behavior. "Transcriptome analysis showed new markedly altered genes (e.g., KLHL1, LHX9, and MGARP) and a large number of differential expression genes (DEGs), some of which are related to autism." (PMID 34567661, 2020).
Cerebellar atrophy (1 paper, 2014). Cerebellar atrophy is defined as a cerebellum with initially normal structures, in a posterior fossa with normal size, which displays enlarged fissures (interfolial spaces) in comparison to the foliae secondary to loss of tissue. "He and collaborators confirmed KLHL1’s physiological role in cerebellar function using targeted deletion of KLHL1 in Purkinje neurons, which resulted in dendritic deficits, mild cerebellar atrophy, abnormal gait and progressive loss of motor coordination in mice." (PMID 25610372, 2014).
childhood asthma (1 paper, 2022). "In a previous genome-wide analysis, the interaction of KLHL1 locus and early life smoke exposure was found to be associated with the onset of childhood asthma." (PMID 35910207, 2022).
COVID-19 (1 paper, 2022). A disease caused by infection with severe acute respiratory syndrome coronavirus 2. "We have detected a significant signal associated with COVID-19 related pneumonia at locus 13q21.33, with a peak residing upstream of the gene KLHL1 (p = 1.91 × 10−8)." (PMID 35910207, 2022).
lung carcinoma (1 paper, 2022). "Moreover, it was shown that an increased mutation rate in the KLHL1 gene was associated with lifetime benzo(a)pyrene exposure in patients with air-pollution-related lung cancers." (PMID 35910207, 2022).
Obesity (1 paper, 2021). Accumulation of substantial excess body fat. "KLHL1 KO mice displayed adult obesity and abnormal re-feeding after overnight fasting." (PMID 34566565, 2021). "Although our systemic KLHL1-KO model is not a good model to explore questions regarding obesity and altered starvation responses changes observed in these mice, we examined the possible contribution of the altered molecular mechanisms observed in the KLHL1 KO to these phenotypes." (PMID 34566565, 2021).
cancer (2 papers, 2016 to 2022). A tumor composed of atypical neoplastic, often pleomorphic cells that invade other tissues. "Two genes, actin-organizing protein KLHL1 at 13q21.33 and COL11A1 (collagen, type XI, alpha 1) at 1p21.1 were detected as joint deletions in all four cancer types (breast, ovarian, endometrial, and cervical, BOEC)." (PMID 27876019, 2016).
tumor (2 papers, 2023). "Compared to primary tumours, CSF cfDNA more frequently lost 13q regions containing PCDH9 and PCDH17 (members of the cadherin superfamily) and KLHL1, an actin binding protein with a role in cytoskeleton reorganisation." (PMID 37973922, 2023).
KLHL1 also shares sentences with these, for which no sentence is quoted: Anxiety (1 paper); glioma (1); pneumonia (1); salpingitis (1).